RUNX3 (RUNX family transcription factor 3)
Diseases named in the same sentence as RUNX3 in open-access papers (continued):
Sharing a sentence is not in itself a finding about the gene and the disease.
cancer (continued). "Moreover, RUNX3 has been reported to inhibit the transcription of HES1, the Notch target gene implicated in stemness, metastasis, and chemoresistance regulation in cancer." (PMID 37759525, 2023). "The prevalence of RUNX3 hypermethylation in cancer and the potential for pharmacological reversion suggest that reactivating the silenced RUNX3 may be a first-line treatment for MYC addiction in such cancers." (PMID 37400551, 2023). "EZH2 has been shown to repress RUNX3 transcription in cancer cell lines." (PMID 36766749, 2023). "Methylation of RUNX3 promoters has an impact on cancers and B-cell maturation." (PMID 36999031, 2023). "We discuss how RUNX3 serves as gatekeeper via its interactions with oncogenic signaling pathways and identify questions that may lead to new insights on cancer stem cell biology." (PMID 36766749, 2023). "RUNX3 strongly influences core cellular processes (e.g., cell cycle and apoptosis) and signaling pathways (e.g., TGFβ, Wnt and Ras) that are frequently altered in cancer." (PMID 36766749, 2023). "Therefore, the development of more potent DNMT1 inhibitors acquiring potential binding pocket features is highly desirable to restore the suppressed TSGs (RUNX3) in cancer therapeutics." (PMID 35898303, 2022). "RUNX proteins not only activate their direct target genes, but also interact with many other TFs involved in various signaling pathways to modulate the development and progression of cancer, such as the ability of RUNX3 to directly interact and suppress the activity of the β-catenin/TCF4 complex." (PMID 36429115, 2022). "In addition, the genes significantly associated to OS were enriched for targets of several key cancer TFs like ELK1, YY1 and RUNX3." (PMID 36584096, 2022). "Therefore, in the present study, a BRN of the DNMT1–RUNX3 signaling was developed to provide an insight into the epigenetic-mediated silencing of RUNX3 leading to cancer development and metastasis." (PMID 35898303, 2022). "Nevertheless, RUNX3-mediated ILC2 immune responses could potentially be an exciting new area of cancer research for future treatment." (PMID 36231078, 2022). "However, the precise mechanism of epigenetic-influenced silencing of the RUNX3 signaling resulting in cancer invasion and metastasis remains inadequately characterized." (PMID 35898303, 2022). "RUNX3 was overexpressed in nine types of cancer and showed low expression in five types." (PMID 35522574, 2022). "RUNX3 plays an inhibitory role as a tumor suppressor gene in a variety of cancers." (PMID 36476345, 2022). "The RUNX3 gene is located on chromosome 1p36, which is a hotspot depleted in various cancer types." (PMID 35522574, 2022). "We also performed Kaplan–Meier survival analysis for RUNX3 within the same types of cancer." (PMID 33672337, 2021). "However, the overexpression of LncRNA GAS5 decreased miR-544 expression, by increasing runt related transcription factor 3 (RUNX3) expression, favouring increased activated NK cell-mediated cytotoxicity suggesting a potential therapeutic target for cancer." (PMID 34303380, 2021). "Additionally, inactivation of RUNX3 expression has been reported in various cancers, such as prostate, lung, pancreas, and breast." (PMID 34884658, 2021). "Eventually, TrkB suppresses BMP and RUNX3-mediated growth inhibition of cancer cells." (PMID 32731498, 2020). "Cancers provide evidence that expression of RUNX3 in metastatic tissue has decreased significantly." (PMID 32765634, 2020). "Therefore, we wanted to determine if CFEF-cetuximab treatments influenced the abundance of RUNX3 in cancer cells." (PMID 32765634, 2020). "RUNX3-mediated reactive oxygen species (ROS) can lead to an enhanced ER stress in cancer cells." (PMID 31022877, 2019).
cancer (continued). "Furthermore, RUNX3 is frequently downregulated epigenetically in various types of cancer, including gastric, breast, lung, pancreas, prostate, oesophagus, and uterine cervix cancer." (PMID 30535344, 2019). "Few cancer epigenetic studies have suggested that RUNX3 downregulation could be the result of hypermethylation of the promoter of RUNX3." (PMID 31467531, 2019). "RUNX3 gene is frequently found to be transcriptionally silenced or deleted in cancer tissues." (PMID 30781778, 2019). "Yet, epigenetic silencing of RUNX3 is extremely common in cancer and often unappreciated." (PMID 30535344, 2019). "It will be informative to see if RUNX3 is functionally active in other TRAIL-resistant cancers." (PMID 31022877, 2019). "There are reports demonstrating that RUNX3 plays a role in cancer development." (PMID 29651226, 2018). "RUNX3 overexpression suppressed migration and invasion in both cancer cells." (PMID 29254144, 2017). "As Runx3 was found acetylated in some cancers, Tcf1 may act directly on Runx3 to modulate CD4 silencing." (PMID 28382035, 2017). "Therefore, we investigated the potential of RUNX3 as a cancer-specific marker for OSCC-mediated bone invasion." (PMID 28030842, 2017). "To identify whether miR-186 controlled RUNX3-induced cancer metastasis inhibition, we miR-186 mimics to up-regulate the expression of miR-186 in RUNX3-overexpressing cells." (PMID 28977878, 2017). "If that turns out to be the case, RUNX3 will be a promising target for curative cancer therapy." (PMID 25961920, 2016). "Various miRNAs targeting RUNX3 have recently been reported in cancer and diseased cells." (PMID 26375442, 2015). "Ultimately, whether RUNX3 P1 methylation can reveal the specific polarity of cancer immune responses, used alone or in combination, awaits formal validation in appropriately powered clinical studies." (PMID 26682246, 2015). "Study demonstrated that RUNX3 is a tumor suppressor gene, which is absent or mutated in several types of cancers including lung due to hemizygous deletions or epigenetic alterations." (PMID 25948105, 2015). "Many reports have shown essential behavior of RUNX3 in a variety of cancers." (PMID 25551195, 2014). "RUNX3 has been shown to be involved in the formation of variety of a human cancers." (PMID 24078903, 2013). "Further, urothelial tissues affected by UC could be clearly distinguished from normal urothelia based on the presence of aberrant DNA methylation regions in cancer-associated genes such as CDH1, RASSF1A and RUNX3 with sufficient sensitivity and specificity." (PMID 23735005, 2013). "A significantly lower expression of RUNX3 was observed in the carcinoma tissues (P = 0.000)." (PMID 23457532, 2013). "Methylation of the RUNX3 promoter is one of the most common aberrant methylation events in cancer." (PMID 21867527, 2011). "In addition, Runx3 is deeply involved in various cancer processes such as cell growth, apoptosis, angiogenesis, and metastasis." (PMID 24250365, 2011). "Importantly, restoration of RUNX3 expression in cancer cell lines leads to apoptosis or decreased proliferation of cancer cells and to their differentiation." (PMID 21203558, 2010). "On the other hand, most cancer cells expressed RUNX3 in their nuclei." (PMID 19521519, 2009). "In this study, we confirmed the low expression of RUNX3 in various cancer cell lines by RT-PCR." (PMID 19521519, 2009). "First of all, RUNX3 is involved in many types of human cancer as a tumour suppressor." (PMID 18727821, 2008). "In conclusion, in HCT116 and HT29 cell strains, knocking out EZH2 may promote expressions of proteins related to the Wnt/β-catenin signaling pathway through inhibiting RUNX3, which in turn suppresses the cancer cellular proliferation, invasion and migration while promoting apoptosis." (PMID 38048186, 2023).
cancer (continued). "However, therapeutic reactivation of RUNX3 expression through epigenetic means may be insufficient to sustain RUNX3 expression as cancer progresses, as many UPS components, including E3 ligases such as MDM2 and Smurfs, are hyperactivated in cancer cells." (PMID 36899853, 2023). "Thus, targeting the UPS may be effective as an adjuvant therapy for alleviating RUNX3 destabilization in cancer." (PMID 36899853, 2023). "This suggests that cancer cells may overexpress kinases to phosphorylate RUNX3 at PY motifs or other target residues that, after cytoplasmic localization, could be recognized by WW domain-containing E3 ligases, such as Smurf1/2, for ubiquitination and proteasomal degradation." (PMID 36899853, 2023). "Thus, a contextual determinant of the dual nature of RUNX3 might be affected by other transcription factors in a cancer context." (PMID 37190031, 2023). "Furthermore, RUNX3 overexpression was recently shown to facilitate the development of a myelodysplastic syndrome in TET2-deficient mice, characterised by a disruption of cancer-related pathways and RUNX1-mediated haematopoiesis." (PMID 35075235, 2022). "Moreover, UC–CRC cases presented much higher methylation levels of RUNX3 than UC controls, indicating that RUNX3 agonists might play an anti-inflammatory and anti-cancer role in clinical settings." (PMID 31737035, 2019). "However, the potential inhibition of RUNX3 by CADD522 could be toxic to normal tissue of other organs in cancer patients." (PMID 29050333, 2017). "However, how RUNX3 is involved in cancer progression remained incompletely understood." (PMID 24447545, 2014). "In addition, HDACi could induce expression of p21 by stabilizing and inducing transcriptional activity of RUNX3, leading to induction of cancer cell apoptosis." (PMID 22928010, 2012). "The percentages of RUNX3+ cells and CD8+RUNX3+T/CD8+T cells were all lower in cancer tissues than in paracancer tissues." (PMID 39822248, 2024). "We also provide a previously unrecognized view of the potential synergisms between RUNX3 and CDX2, LHX2 and TCF3 in promoting the transcription of genes involved in cancer stem cell regulation and metastasis." (PMID 38240752, 2024). "Further in-depth studies of the RUNX3-MYC relationship will improve our understanding of the interplay between RUNX family members and MYC in cancer biology." (PMID 37400551, 2023). "For example, a recent study demonstrated that a small peptide, RMR, inhibits phosphorylation of RUNX3 at T209 by PAK1, effectively suppressing cancer cell proliferation and cancer formation." (PMID 36899853, 2023). "Together, these perspectives provide a comprehensive look at RUNX3–UPS interactions, from which to gain new insights into cancer physiology." (PMID 36899853, 2023). "Methylation levels of a 4 gene-panel (RUNX3, p16, RASSF1A, and CDH1) showed 89% sensitivity and 100% specificity for cancer detection." (PMID 36980276, 2023). "A schematic model depicting the stepwise process of replication and methylation of TSG RUNX3 by DNMT1 and its subsequent influence on various cancer signaling pathways was established using the literature-driven information." (PMID 35898303, 2022). "Our general aim was to examine the use of RUNX3 as a prognostic indicator of CCRCC and its potential use as a target for the treatment of this cancer." (PMID 36518886, 2022). "RUNX3 has potential use as a biomarker for prognostic monitoring of CCRCC and as a therapeutic target for the treatment of this cancer." (PMID 36518886, 2022). "In contrary to RUNX1 and RUNX3, RUNX2 promoted cancer cell recruitment and adhesion in bone and further facilitated bone colonization." (PMID 36092942, 2022).
cancer (continued). "Exosomal miR-17-5p secreted by CAFs targets RUNX3 in cancer cells, which enables MYC to activate the transcription of TGF-β1 to promote metastasis and, in turn, activate fibroblasts, forming a cancer positive feedback loop." (PMID 34572947, 2021). "We also found that upregulation of both RUNX3 and CLDN1 enhanced the sensitivity of cancer cells to cisplatin and induced cell death." (PMID 32754286, 2020). "However, some evidence suggests that RUNX3 may have oncogenic role in cancer." (PMID 32943993, 2020). "Extensive genes have been identified as the target of miR-761 in numerous cancers, including HDAC1, Rab3D, Runx3, Mitofusin-2, CXCR1, TRIM29, MSI1, ING4, TIMP2, and GSK3β." (PMID 32185226, 2020). "RUNX3, a member of the RUNX family, has been shown to participate in various cancer pathways, including cell growth, apoptosis, and angiogenesis." (PMID 30944663, 2019). "Subgroup meta-analysis by geographical populations was performed for p16, RASSF1A, GSTP1, APC and RUNX3 between HBV-positive carcinoma tissues and HBV-negative carcinoma tissues." (PMID 31772678, 2019). "The meta-analysis of GSTP1, RUNX3, SOCS1, CDH1 and SFRP1 genes methylation was performed between HBV-positive carcinoma tissues and HBV-negative carcinoma tissues and between HBV-positive adjacent tissues and HBV-negative adjacent tissues." (PMID 31772678, 2019). "In the present study, the smoking-related methylation changes to RUNX3, IL6R, PTAFR, and ANKRD11 (cardiovascular-related genes) and CEP135 and CDH23 (cancer-related genes) corresponded to increased gene expression." (PMID 26756918, 2016). "The human runt-related transcription factor 3 (RUNX3), an important component of the TGF-β signaling pathway, is deleted in a variety of human cancers, including ESCC." (PMID 27110300, 2016). "Among these, RUNX3, the smallest member of RUNX family, reported to be involved in various cancer processes, such as cell growth, apoptosis, angiogenesis, and metastasis." (PMID 25948105, 2015). "We provide evidence that RUNX3 plays a significant role in regulating the EMT, thereby contributing to cancer progression." (PMID 24447545, 2014). "The region contains multiple genes with a known or suspected role in cancer including ARID1A, E2F2, NBPF1, PAX7, RUNX3 and SDHB." (PMID 25420937, 2014). "RUNX3 was originally cloned as AML2 and is localized on chromosome 1p36.1, which is among the most frequently affected regions in various types of cancers." (PMID 23457532, 2013). "In a sharp contrast to RUNX1 and RUNX3, oncogenic property of RUNX2 has been postulated in several human cancers." (PMID 24078903, 2013). "Three members of the Runx family genes, RUNX1, RUNX2 and RUNX3, and related gene, CBFB/Pebpb2, are all known as the developmental regulators and have been shown to be important in human cancers." (PMID 19521519, 2009). "Overall, gene methylation frequencies were higher among MSI than among MSS carcinomas, and were statistically significant for CRABP1, MLH1, NR3C1, RUNX3, and SCGB3A1 (P ≤ 0.0001, P ≤ 0.0001, P = 0.001, P ≤ 0.0001, and P = 0.03, respectively)." (PMID 19117505, 2008). "Hypermethylated CRABP1, MLH1, NR3C1, RUNX3, and SCGB3A1 were shown to be identifiers of carcinomas with microsatellite instability." (PMID 19117505, 2008). "We examined the hypermethylation status of a panel of 5 normally unmethylated tumor suppressor or cancer genes: FHIT, FANCF, Cyclin-D2, BRCA2 and RUNX3 in 25 ovarian GCTs and ovarian cell line DNAs using the MSP assay." (PMID 15574200, 2004).
cancer (continued). "Runx3 promotes CD8+ TRM cell development and viability; increasing its levels may enhance treatment strategies for infectious diseases and cancer." (PMID 39802636, 2025). "Normal A and cancer 0 clusters shared expression of heat shock protein A (HSPA) and insulin growth factor–binding protein (IGFBP) genes, engagement of the heat shock factor 1 signaling pathway, and activity of SNAI1, RUNX3, and TBX15 transcription factors." (PMID 40215177, 2025). "The successful generation of RUNX3 knockout pigs exhibited a lack of RUNX3 expression, making them potentially useful models for human cancer studies, which enhanced the understanding of cancer mechanisms and the development of new treatments." (PMID 39595585, 2024). "We demonstrated positive correlation between RUNX3 and WNT5A expression in resected cancer tissue." (PMID 38240752, 2024). "In oral squamous cell carcinoma, RUNX3 also inhibits VEGF activity and exerts anti-cancer effects." (PMID 38430423, 2024). "These two differences were both statistically significant, while the difference in the percentage of CD103+CD8+RUNX3+T among CD8+T cells between cancer or paracancer tissues was not statistically significant." (PMID 39822248, 2024). "Hemizygous deletion of Runx3 in BALB/c mice was enough to induce the spontaneous development of mammary ductal carcinoma with increased Ki67 staining, confirming a hyperproliferative phenotype in the cancer cells." (PMID 36831308, 2023). "The authors further demonstrated that RUNX3 responded to and interacted with SMAD4 status to regulate the balance between cancer cell division and dissemination, and they suggested that RUNX3 and SMAD4 levels can be used together to inform clinical decision-making for resectable PDAC." (PMID 37596627, 2023). "In contrast to RUNX1 and RUNX3, which may function as oncogenes or tumor suppressors, RUNX2 is mostly overexpressed and oncogenic in human cancer." (PMID 37190015, 2023). "To rule out the antitumor role of Runx3 in cancer cells, we constructed conditional knockout mice to prove the specific function of Runx3 in T cells and immunotherapy." (PMID 37189103, 2023). "The detected cancer genes NOTCH1 and RUNX1 could possibly influence the RUNX3 signaling pathway and could be meaningful for metastases formation." (PMID 38010391, 2023). "Thus, our findings demonstrated that RUNX3 inhibited the invasion and migration of CCRCC, similar to its function in other cancers." (PMID 36518886, 2022). "Hence, RUNX3 has important roles in restraining the pathogenicity of CD4+ CTL cells in tissue inflammation and cancer development." (PMID 36231078, 2022). "Another positive biomarker was RUNX3 (selected for 16 cancer types), which plays a role in the TME regulating hypoxia and immune-cell infiltration, and has been suggested as a potential target to prevent immune escape of cancer cells." (PMID 34430923, 2021). "In gastric cancer, RUNX3 participates in TGF-β1-dependent cell growth suppression by binding to promoter p21 and inducing expression of CDKN1A (cyclin-dependent kinase inhibitor) that leads to inhibition of cancer cell proliferation." (PMID 34884658, 2021). "Meanwhile, ex vivo studies of cytotoxic CD4+ T cells from human cancer patients points to variable overexpression of either TBX21 or RUNX3 plus BLIMP-1 (via PRDM1) when compared with non-cytotoxic CD4+ T cells." (PMID 34910940, 2021). "Additionally, one transcription activator, RUNX3, can directly bind the CLDN1 promoter and drive CLDN1 transcription, leading to suppression of cancer progression." (PMID 32754286, 2020).